DNAJC3 (DnaJ heat shock protein family (Hsp40) member C3)
Description:
Involved in the unfolded protein response (UPR) during endoplasmic reticulum (ER) stress. Acts as a negative regulator of the EIF2AK4/GCN2 kinase activity by preventing the phosphorylation of eIF-2-alpha at 'Ser-52' and hence attenuating general protein synthesis under ER stress, hypothermic and amino acid starving stress conditions (By similarity). Co-chaperone of HSPA8/HSC70, it stimulates its ATPase activity. May inhibit both the autophosphorylation of EIF2AK2/PKR and the ability of EIF2AK2 to catalyze phosphorylation of the EIF2A. May inhibit EIF2AK3/PERK activity.
Synonyms: ERdj6; P58IPK; PRKRI; P58; HP58; p58(IPK); ACPHD
Tractability: Antibody: its Gene Ontology location is reachable by antibodies, with high confidence; UniProt predicts a signal peptide or a membrane-spanning region. PROTAC: ubiquitination databases record sites on it; its protein half-life has been measured.
Gene: Protein-coding gene on chromosome 13 (95,677,114 to 95,794,988, forward strand). Ensembl gene ENSG00000102580.
Subcellular location: Endoplasmic reticulum
Subcellular location (Human Protein Atlas): Endoplasmic reticulum
Pathways (Reactome):
Disease: Maturation of DENV proteins; Viral mRNA Translation
Immune System: Neutrophil degranulation; PKR-mediated signaling
Metabolism of proteins: Post-translational protein phosphorylation; Regulation of Insulin-like Growth Factor (IGF) transport and uptake by Insulin-like Growth Factor Binding Proteins (IGFBPs)
Cellular responses to stimuli: XBP1(S) activates chaperone genes
Gene Ontology:
Molecular function: misfolded protein binding; protein kinase binding; protein kinase inhibitor activity; protein-folding chaperone binding
Biological process: negative regulation of apoptotic process; negative regulation of translation in response to endoplasmic reticulum stress; cellular response to cold; negative regulation of endoplasmic reticulum stress-induced eIF2 alpha phosphorylation; positive regulation of translation initiation in response to endoplasmic reticulum stress; protein folding in endoplasmic reticulum; endoplasmic reticulum unfolded protein response; response to endoplasmic reticulum stress
Cellular component: extracellular exosome; extracellular vesicle; membrane; azurophil granule lumen; cytoplasm; cytosol; endoplasmic reticulum; endoplasmic reticulum lumen; extracellular region
Genetic constraint (gnomAD): Loss-of-function variants: 33 observed, 59.81 expected, observed/expected ratio (o/e) 0.55, 90% interval 0.42 to 0.74. The upper end of that interval is the gene's LOEUF score, 0.74, which puts it in group 3 of 6, group 1 being the genes least tolerant of losing a copy. Missense variants: 506 observed, 574 expected, observed/expected ratio (o/e) 0.88, 90% interval 0.82 to 0.95. Synonymous variants: 194 observed, 197.5 expected, observed/expected ratio (o/e) 0.98, 90% interval 0.87 to 1.11.
Homologues: Orthologues: chimpanzee DNAJC3 (99% identical), macaque DNAJC3 (99% identical), pig DNAJC3 (98% identical), mouse Dnajc3 (97% identical), rat Dnajc3 (94% identical), guinea pig DNAJC3 (93% identical), rabbit DNAJC3 (92% identical), dog DNAJC3 (87% identical), tropical clawed frog dnajc3 (75% identical), zebrafish dnajc3a (71% identical), Caenorhabditis elegans dnj-7 (44% identical), Drosophila melanogaster P58IPK (43% identical), and 7 more. Paralogues in human: DNAJC13 (17% identical), DNAJC1 (12% identical), DNAJC16 (12% identical), DNAJC21 (12% identical), DNAJC14 (11% identical), DNAJC10 (11% identical), DNAJC11 (11% identical), DNAJC7 (11% identical), DNAJC2 (10% identical), DNAJC17 (9% identical), DNAJC5 (9% identical), DNAJC25 (9% identical), and 8 more.
Diseases named in the same sentence as DNAJC3 in open-access papers:
DNAJC3 is named in the same sentence as 59 diseases in open-access papers, as found by Europe PMC text mining. Sharing a sentence is not in itself a finding about the gene and the disease. The quoted sentences say what the papers report.
diabetes (17 papers, 2008 to 2026). "Clinically, patients bearing loss-of-function mutations of DNAJC3 (p58IPK) suffer from diabetes and multisystemic neurodegeneration." (PMID 37371028, 2023). "Recessive loss of function mutations of DNAJC3 have been found by exome and genome sequencing to cause early HI evolving into diabetes for insulin insufficiency, growth retardation and neurodegeneration in four children." (PMID 35422763, 2022). "The pathomechanism of diabetes caused by DNAJC3 mutations further involves mitochondrial degeneration." (PMID 34356055, 2021). "Recessive mutations in DNAJC3, an endoplasmic reticulum (ER)-resident BiP co-chaperone, have been identified in patients with multisystemic neurodegeneration and diabetes mellitus." (PMID 34692675, 2021). "The fact that ERj6 (DNAJC3) is involved in Sec61 channel closure and that its absence in human patients, too, causes Diabetes mellitus is in perfect line with this interpretation." (PMID 33925740, 2021). "Mutations leading to loss of another ER-DNAJ family protein, DNAJC3, have been shown to result in pancreatic β-cell failure and diabetes in mice." (PMID 33584694, 2020). "Clinically, patients bearing loss-of-function mutations in the DNAJC3 gene, which encodes p58IPK, suffer from diabetes and multisystemic neurodegeneration." (PMID 30245625, 2018). "Further clinical studies should be conducted to determine whether PBA preserves beta-cell function in humans and thus delays the onset of diabetes mellitus in DNAJC3-deficient individuals." (PMID 38279270, 2024). "Mutations of DNAJC3 have been implicated in diabetes and neurodegeneration." (PMID 32576858, 2020). "Bi-allelic loss-of-function mutations in DNAJC3, encoding a co-chaperone of BiP, one of the major chaperones of the ER, have been shown to cause neurodegeneration with early-onset ataxia, upper-motor-neuron signs, demyelinating neuropathy, and cerebral atrophy associated with diabetes mellitus." (PMID 34692675, 2021). "The DNAJC3-related pathogenicity involves a systematic phenotype, including the early onset of diabetes mellitus and different neurological disorders." (PMID 35054769, 2022). "Symptoms resulting from mutations in DNAJC3 are partially overlapping with phenotypes caused by mutations in DNAJB2 and SIL1, but with the addition of diabetes." (PMID 34692675, 2021). "However, an explanation for the bi-phasic phenotype of DNAJC3 deficiency in humans, with hyperinsulinemic hypoglycemia that remits in childhood/adolescence, eventually evolving into diabetes later in life, has not yet been found." (PMID 38279270, 2024). "Consistent with the animal findings, pedigree analysis and whole exome sequencing in two index families also revealed that a loss of function DNAJC3 mutation (resulting in absence of DNAJC3 protein in ER) manifested as monogenic diabetes and multisystemic neurodegeneration." (PMID 33584694, 2020). "Amidst the subset of DEGs, the prominent gene signatures include INS, INSR, DNAJC3, OMA1, GOS2, and CALR which have been reported to be differentially expressed in type 2 diabetes mellitus and/ or metabolic disorders." (PMID 37943808, 2023). "Preclinical data on the role of DNAJC3 in maintaining ER homeostasis and, in particular, beta-cell survival are consistent with the development of diabetes mellitus in the absence of DNAJC3." (PMID 38279270, 2024).
Hyperglycemia (8 papers, 2008 to 2024). An increased concentration of glucose in the blood. "In mice, knockout of Dnajc3 causes beta-cell apoptosis, accompanied by hypoinsulinemia and the gradual onset of hyperglycemia as the mice mature." (PMID 38279270, 2024). "In mice, Dnajc3 knockout results in the gradual onset of hyperglycemia as a consequence of beta-cell apoptosis, reduced beta-cell mass, and hypoinsulinemia at adult maturity." (PMID 38279270, 2024).
viral infection (6 papers, 2008 to 2025). "DNAJC3 (p58IPK), an ER luminal co-chaperone involved in the unfolded protein response, is also implicated in viral infections, but its function is again chaperone-like rather than membrane-bending." (PMID 41012666, 2025). "The protein DNAJC3 acts as an inhibitor of the interferon-induced, dsRNA-activated protein kinase (PKR), which plays a major role in mediating the interferon response to viral infection." (PMID 18373840, 2008).
Ataxia (4 papers, 2020 to 2024). Ataxia refers to impaired coordination of voluntary muscle movement. "We, therefore, supplemented the EOAD- control group with ataxia genotypes that were not reported with comorbid dystonia in literature (including ABHD12; IFRD1; KIAA0226; PHYH; TDP1; VWA3B; GTF2H5; FLVCR1; ACO2; HSD17B4; DNAJC3 gene mutations; PubMed and OMIM)." (PMID 33255407, 2020).
COVID-19 (2 papers, 2022 to 2025). A disease caused by infection with severe acute respiratory syndrome coronavirus 2. "Members of the MYB family, including DANJ homolog subfamily C member 3 (DNAJC3) was significantly upregulated in the plasma of PLWH with COVID-19." (PMID 40568587, 2025).
Insulin resistance (2 papers, 2013 to 2020). Increased resistance towards insulin, that is, diminished effectiveness of insulin in reducing blood glucose levels. "The endoplasmic reticulum stress-related genes (DNAJB9, DNAJC3) and those involved in insulin resistance (PRKCε) were all strongly upregulated in NAFLD patients." (PMID 32429478, 2020).
ischemia (2 papers, 2009 to 2023). A hypoperfusion of the BLOOD through an organ or tissue caused by a PATHOLOGIC CONSTRICTION or obstruction of its BLOOD VESSELS, or an absence of BLOOD CIRCULATION. "Thus, the present observation of METH-induced Dnajc3/p58IPK does suggest its participation in a coordinated response to attenuate or prevent METH-mediated deleterious effects on the ER in conjunction with VEGF which has been shown to protect neurons against ischemia glutamate toxicity and ER stress." (PMID 19564919, 2009).
bipolar disorder (1 paper, 2007). A disorder of the brain that causes unusual shifts in mood, energy, activity levels and the ability to carry out day-to-day tasks. "For example, 10 genes among the 16 confirmed genes (Cacng2, Dnajc3, Dusp4, Gpc6, Mbp, Nov, Phf21b, Atxn10, Xbp1, and Zfyve28) have their human orthologs located within a 10 Mb region flanking the linkage markers for bipolar disorder, and thus merit further study." (PMID 18028544, 2007).
cerebellar degeneration (1 paper, 2021). Degeneration of the cerebellum. "Remarkably, a modulating function of DNAJC3 expression in cerebellar degeneration has been demonstrated in the molecular etiology of MSS, demonstrating a crucial role of this co-chaperone in neuronal maintenance." (PMID 34692675, 2021).
glioma (1 paper, 2025). A benign or malignant brain and spinal cord tumor that arises from glial cells (astrocytes, oligodendrocytes, ependymal cells). "In this study, proteomic techniques and bioinformatics analysis were employed to confirm a significant overexpression of DNAJC3 in glioma tissues, which is associated with poor patient prognosis." (PMID 41391769, 2025). "Given that multiple immune-related signaling pathways were significantly associated with the DNAJC3 high-expression group, we further explored the relationship between DNAJC3 and the glioma immune microenvironment using various algorithms." (PMID 41391769, 2025). "In our study, we found that high expression of DNAJC3 is closely associated with the infiltration of immune cells in glioma." (PMID 41391769, 2025). "Analysis of the glioma sequencing data from the TCGA database revealed a marked association between high expression of DNAJC3 and poor prognosis in glioma patients, suggesting that DNAJC3 might be a potential oncogenic factor." (PMID 41391769, 2025). "In summary, this study suggests that DNAJC3 may be a potential oncogene, and its high expression is associated with poor prognosis in glioma patients." (PMID 41391769, 2025). "In addition, drug sensitivity analysis suggested that DNAJC3 expression may be associated with resistance to mitogen-activated protein kinase kinase inhibitors in glioma patients." (PMID 41391769, 2025). "However, the precise role of DNAJC3 in the progression of gliomas and the underlying mechanisms by which it exerts its effects currently remain unclear." (PMID 41391769, 2025). "Subsequently, a series of cellular functional experiments were conducted to validate the important role of DNAJC3 in the malignant progression of glioma." (PMID 41391769, 2025). "We utilized gene set enrichment analysis (GSEA) to explore the molecular mechanism by which DNAJC3 regulates the malignant progression of glioma." (PMID 41391769, 2025). "Subsequently, by integrating the quantitative information of immunohistochemical images from the Human Protein Atlas public database, the expression levels of DNAJC3 in normal tissues and glioma tissues were further verified." (PMID 41391769, 2025). "WB further validated that the MAPK–ERK and PI3K–AKT signaling pathways are involved in the process of DNAJC3-driven malignant progression of gliomas." (PMID 41391769, 2025). "In this study, we employed proteomic profiling combined with public databases to screen for differentially expressed proteins and found that DNAJC3 was significantly overexpressed in glioma." (PMID 41391769, 2025). "To investigate the regulatory role of DNAJC3 in the malignant phenotypes of glioma, we successfully constructed DNAJC3 knockdown and overexpression cell models." (PMID 41391769, 2025). "Based on the transcriptome sequencing data of 702 glioma patients from The Cancer Genome Atlas (TCGA) database, we explored the correlation between DNAJC3 and the clinicopathological characteristics of glioma patients." (PMID 41391769, 2025). "The results also confirmed a significant correlation between DNAJC3 expression and the clinicopathological characteristics of glioma patients, which was consistent with the findings based on the TCGA database." (PMID 41391769, 2025). "In this study, which utilized LC–MS/MS technology, we found that the ERS-related protein DNAJC3 was significantly overexpressed in glioma tissues." (PMID 41391769, 2025). "Further in-depth analysis of the relationship between DNAJC3 expression levels and immune cell infiltration in glioma revealed that DNAJC3 may possess immunosuppressive properties." (PMID 41391769, 2025). "This suggests that high expression of DNAJC3 may promote the formation of an immunosuppressive tumor microenvironment in glioma." (PMID 41391769, 2025). "This suggests that DNAJC3 may promote the malignant progression of glioma by activating the MAPK–ERK and PI3K–AKT signaling pathways." (PMID 41391769, 2025).
glioma (continued). "In addition, bioinformatics analysis was utilized to analyze the impact of DNAJC3 expression on the immune microenvironment of gliomas." (PMID 41391769, 2025). "Preliminary exploration has revealed that DNAJC3 may promote the malignant progression of gliomas by activating the MAPK–ERK and PI3K–AKT signaling pathways, as well as regulating immune cell infiltration." (PMID 41391769, 2025). "Through a series of cellular functional experiments, we further investigated the regulatory role of DNAJC3 on the malignant phenotypes of gliomas, including proliferation, migration, invasion, and apoptosis, thereby elucidating its crucial role in the malignant progression of gliomas." (PMID 41391769, 2025). "The results also demonstrated a significant increase in DNAJC3 in glioma tissues." (PMID 41391769, 2025). "Collectively, these findings suggest that the ER stress–induced aberrant expression of DNAJC3 may play a pivotal regulatory role in the malignant progression of glioma." (PMID 41391769, 2025). "Moreover, the specific mechanism of how DNAJC3 regulates the immune microenvironment of glioma remains a key area for future research." (PMID 41391769, 2025). "This implies that DNAJC3 may drive the progression of glioma by activating these two classical oncogenic signaling pathways." (PMID 41391769, 2025). "In conclusion, this study found that DNAJC3 may play a significant role in the malignant progression and immune evasion of glioma, suggesting its potential as a therapeutic target." (PMID 41391769, 2025). "The results showed that DNAJC3 was specifically highly expressed mainly in macrophages and astrocytes, suggesting that these two types of cells may be the key effector cells through which DNAJC3 regulates the glioma immune microenvironment." (PMID 41391769, 2025). "The results showed that the expression level of DNAJC3 in glioma tissues was significantly higher than that in normal brain tissues, which was consistent with the previous experimental results." (PMID 41391769, 2025).
Hepatic steatosis (1 paper, 2024). Steatosis is a term used to denote lipid accumulation within hepatocytes. "Mice with genetic deletions of either ER stress-sensing pathways (ATF6α, eIF2α, IRE1α) or quality control (Dnajc3) show a similar response to ER stress, including the development of hepatic steatosis." (PMID 38279270, 2024).
hyperinsulinemic hypoglycemia (1 paper, 2024). An inherited autosomal recessive syndrome characterized by the disorganized formation of new islets in the pancreas and congenital hyperinsulinism. "Recently, it has been recognized that hyperinsulinemic hypoglycemia is part of a syndrome caused by biallelic loss-of-function mutations in the DnaJ Heat Shock Protein Family (Hsp40) Member C3 gene (DNAJC3, also known as P58IPK)." (PMID 38279270, 2024). "It is noteworthy that in our individual (Individual 1), apart from hyperinsulinemic hypoglycemia and short stature, there were no other symptoms suggestive of DNAJC3 deficiency in early childhood." (PMID 38279270, 2024).
hyperinsulinism (1 paper, 2024). Abnormally high levels of insulin in the blood. "Clinicians should screen for HH in DNAJC3 deficiency and consider DNAJC3 variants in the differential diagnosis of congenital hyperinsulinism." (PMID 38279270, 2024).
Hypoglycemia (1 paper, 2024). A decreased concentration of glucose in the blood. "A fatty liver phenotype, impaired gluconeogenesis, and depletion of hepatic glycogen stores have been proposed as alternative mechanisms for hypoglycemia in DNAJC3 deficiency." (PMID 38279270, 2024). "The driving factor causing hypoglycemia in DNAJC3 deficiency appears to be increased islet insulin secretion, possibly caused by uncontrolled calcium leakage from the ER via the Sec61 complex, rather than insulin leakage from dying beta cells." (PMID 38279270, 2024).
Peri-Implantitis (1 paper, 2019). An inflammatory process with loss of supporting bone in the tissues surrounding functioning DENTAL IMPLANTS. "The possible mechanisms of SEC61A1 (Sec61 Translocon Alpha 1 Subunit) in T2DM and peri-implantitis appear to be similar to those of the DNAJC3 gene." (PMID 31275749, 2019). "Three leader genes (PSMD10, SOS1, WASF3), eight cross-talk genes (PSMD10, PSMD6, EIF2S1, GSTP1, DNAJC3, SEC61A1, MAPT, and NME1), and one signaling pathway (IL-17 signaling) emerged as peri-implantitis and T2DM linkage mechanisms." (PMID 31275749, 2019).
schizophrenia (1 paper, 2023). A major psychotic disorder characterized by abnormalities in the perception or expression of reality. "Previous studies have shown that genes such as PMAIP1, DNAJC3, DFFA, and BTG3 are involved in apoptosis, but their specific mechanism of action in schizophrenia needs to be further explored." (PMID 37383091, 2023).